LINC01526 (long independently transcribed non-coding RNA 1526)
Synonyms: Lnc-FAM46A-1
Gene: Long non-coding RNA gene on chromosome 6 (81,764,154 to 81,820,202, reverse strand). Ensembl gene ENSG00000224995.
Diseases named in the same sentence as LINC01526 in open-access papers:
LINC01526 is named in the same sentence as 4 diseases in open-access papers, as found by Europe PMC text mining. Sharing a sentence is not in itself a finding about the gene and the disease. The quoted sentences say what the papers report.
gastric cancer (2 papers, 2021 to 2022). A primary or metastatic malignant neoplasm involving the stomach. "We found that LILNC01526 was highly expressed in gastric cancer tissues and cells, and LINC01526 overexpression was associated with a poor prognosis for GC patients." (PMID 36230863, 2022). "In summary, LINC01526 promoted gastric cancer progression by interacting with TARBP2, which subsequently degraded GNG7 mRNA." (PMID 36230863, 2022). "Through expression and functional analyses, we obtained a preliminary understanding of the pro-cancer role of LINC01526 in gastric cancer." (PMID 36230863, 2022). "We found that LINC01526 was upregulated in gastric cancer cells and tissues." (PMID 36230863, 2022). "However, the function and mechanism of LINC01526 in gastric cancer remain unknown." (PMID 36230863, 2022).
tumor (1 paper, 2022). "To further elucidate the role of LINC01526 in GC tumorigenesis in vivo, we established a xenograft tumor-bearing nude mouse model by injecting HGC-27 cells stably expressing sh-LINC01526 or an empty vector to nude mice (n = 5)." (PMID 36230863, 2022).
LINC01526 also shares sentences with these, for which no sentence is quoted: cancer (2 papers); osteosarcoma (1).